STAT3 (signal transducer and activator of transcription 3)
Diseases named in the same sentence as STAT3 in open-access papers (continued):
Sharing a sentence is not in itself a finding about the gene and the disease.
cancer (continued). "In addition, IL-6/JAK/STAT3 pathway inhibition has a synergistic antitumor effect with conventional cancer treatments, e.g., its effect is enhanced in combination with chemotherapy and radiotherapy." (PMID 35089951, 2022). "In both cancers, gastric and esophagus, IL-32 upregulation was coupregulated with proinflammatory cytokines such as TNF-α, IL-1β, and IL-6, suggesting its induction via NF-κB and STAT3 signaling pathways was linked to poor-prognosis cases." (PMID 35281008, 2022). "Our data confirm that STAT3 mutations are not enriched in MS and suggest that the STAT3 hotspot, originally identified in cancer, is not disease-specific." (PMID 36618380, 2022). "Ablation of STAT3 in CD8+ T cells increased their anti-cancer activity." (PMID 36291659, 2022). "Thus, we postulated several molecular candidates, including AKT and STAT3, which contribute not only to cancer cell proliferation but also to the emergence of EGFR TKI resistance." (PMID 35408753, 2022). "These could bring new and important data about the role of STAT3 and autophagy on cancer cachexia and RT-protection effects." (PMID 35847939, 2022). "Unlike classical Stat signaling, which is transient in non-transformed cells, the aberrant-activation of Stat3 occurs in malignant transformation and is implicated in breast and many other human cancers." (PMID 35276290, 2022). "Here, we addressed the intermolecular interaction between Pdia4 and Stat3 in cancer stroma." (PMID 35170261, 2022). "The upregulation of IL-6 can amplify the metabolic cross-disorder STAT3 pathway between the two cells through the IL-6 signal, and CD36 has recently been shown to be a downstream target for activating STAT3, which will further promote fatty acid uptake of cancer cells." (PMID 36106333, 2022). "Alternately, the STAT3 pathway is connected to the development of cancer." (PMID 36497125, 2022). "Replacement of tyrosine 705 with phenylalanine facilitated inactivating STAT3 in cancer cells." (PMID 35690866, 2022). "Investigations indicate a correlation between STAT3 signaling and cancer cell metabolism." (PMID 36033954, 2022). "Though understanding is limited, STAT3 inhibition is another pathway target in cancer cachexia." (PMID 35326491, 2022). "The transcription factor STAT3 has a key role in the onset and progression of cancer." (PMID 35163058, 2022). "Interleukin-6 (IL-6) is a critical mediator of HCC development and is involved in the regulation of cancer stem cell proliferation, differentiation, invasion, metastasis, and angiogenesis through a number of signaling pathways, such as STAT3 signaling, which drives cancer progression and metastasis." (PMID 35432524, 2022). "Furthermore, it is clear that in addition to STAT3 signaling various groups of molecules are involved in cancer development." (PMID 36010693, 2022). "Src, being the first oncogene to be discovered, is important due to its convergence with many upstream stimuli, its cross-talk with other potential molecular targets, such as STAT3, and its ability to modify the cell cytoskeleton, making it important in cancer invasion and metastasis." (PMID 36145523, 2022). "Notably, when the study was initiated, BBI608 was thought to be a STAT3 and a cancer stemness inhibitor." (PMID 35267638, 2022). "STAT3’s target genes are mainly implicated in processes of cell differentiation, such as survivin (BIRC5), B-cell lymphoma (Bcl)-2, cyclin D1, c-Myc or vascular endothelial growth factor (VEGF), thus their expression plays a key role in cancer promotion." (PMID 36185259, 2022). "Interestingly, it was reported that the activated IL-6/JAK2/STAT3 pathway can inhibit bax/bcl2 related caspase-dependent apoptosis, leading to the promotion of proliferation and metastasis of cancer cells." (PMID 36431925, 2022).
cancer (continued). "These modifications may enable the agent to effectively concentrate at its target sites and regulate the intracellular molecular targets (Nrf2, STAT3, etc.)to counteract cancer." (PMID 36145523, 2022). "Overall, these findings reveal a regulatory node within the STAT3 pathway that may be important for the initiation and treatment of STAT3-driven cancers." (PMID 34953855, 2022). "Hence, various small molecule STAT3 inhibitors are in clinical trials as a part of targeted therapy in cancer." (PMID 35928273, 2022). "The STAT3 signaling pathway is considered important for muscle wasting in CC and other conditions with elevated IL-6, while STAT3 inhibition prevents CC in preclinical cancer models." (PMID 35088134, 2022). "Additionally, there is increasing interest in the ability of phosphorylated and acetylated STAT3 to localize to the mitochondria, where it increases mitochondrial gene transcription and ATP production, aiding the Warburg Effect in cancer cells." (PMID 35406557, 2022). "In an in vitro co-culture model of gastric cancer cells and cancer-associated fibroblasts where high IL-11 secretion was measured, treatment with an IL-11 neutralizing antibody significantly inhibited JAK/STAT3 activity leading to reduced cell migration and invasion." (PMID 35053592, 2022). "The OSM/gp130/STAT3 pathway is also correlated with cancer malignancy." (PMID 35565185, 2022). "It acts through the inhibition of STAT3 in all these cancers." (PMID 36428575, 2022). "STAT3 is a signal transducer and activator of the transcription protein family, and its abnormal activation is related to the occurrence and development of several malignant tumors." (PMID 35154350, 2022). "By secreting IL-6, mutant KRAS cancer cells can activate Janus activated kinase 1 (JAK1) to induce the phosphorylation of the transcription factor signal transducer and activator of transcription 3 (STAT3) which is found in immune components such as macrophages of the TME." (PMID 36074553, 2022). "Some of the significant cancer hallmark terms are inflammatory response (CD14, CD69, IL10RA), KRAS signaling up (CD37, IL10RA, GPNMB), IL-6/JAK/STAT3 signaling (CD14, CSF2RB), Interferon Gamma Response (CD69, CSF2RB, IL10RA, VCAM1, SLAMF7), TNF-alpha Signaling via NF-kB (CD69)." (PMID 35486660, 2022). "Among SLs family, we chose ALT and Brv-A for the current study, as 1) the anti-cancer effect and their pivotal role in the inhibition of STAT3 signaling has been extensively reported 2) we confirmed that STAT3, FUT4, and P-GP were the common targets of ALT and Brv-A." (PMID 35281907, 2022). "Moreover, Bcl-3 can induce the STAT3 gene in human cancer cells, while STAT3 can reciprocally induce Bcl-3 expression in mammary epithelial cells." (PMID 35681213, 2022). "Additionally, STAT3 induces the resistance of prostate cancer to chemoradiation and small-molecule inhibitors, reflecting the roles in cancer development." (PMID 36227136, 2022). "Thus, by regulating exosome biogenesis, the activation of STAT3/PKM2/SNAP23 pathway contributes to cancer cachexia development." (PMID 36320056, 2022). "LncRNA RPSAP52 exerted anti-cancer effects via modulating miR-665/STAT3 in GC." (PMID 35322746, 2022). "Furthermore, TNC-induced cytokines, such as IL-1β and IL-6, and transcription factors, such as NF-κB and signal transducer and activator of transcription 3 (STAT3), have been implicated in cancer-related inflammation." (PMID 36033448, 2022). "We hypothesize cancer cells with greater basal STAT3 activity will trap SBT-100 within the cytoplasm to a greater extent, thereby enhancing SBT-100′s ability to inhibit KRAS." (PMID 35886918, 2022). "B7-H4 expression is upregulated by STAT3 activation via PKCδ and plays roles in PKCδ-induced cancer cell motility and metastasis, suggesting that the PKCδ/STAT3/B7-H4 axis may be a potential therapeutic target for CRC." (PMID 35410218, 2022). "Cancer cells undergoing rapid proliferation require persistent STAT3 activation." (PMID 36145523, 2022).
cancer (continued). "Targeting the STAT3 signaling pathway is a promising therapeutic strategy for numerous cancers." (PMID 36000726, 2022). "Induction of IL-6 led to phosphorylation of STAT3 via JAK, resulting in downregulation of ER, occurrence of EMT and cancer stem-like phenotype that could be counteracted by Napabucasin, a newly developed small inhibitor of STAT3." (PMID 35712501, 2022). "STAT3 activation in epithelial cells can also contribute to cancer progression." (PMID 36291659, 2022). "Additionally, MMP overexpression contributes to cancer cell invasion and metastasis, and IL‐8/STAT3 signaling in HNSCC can also upregulate the expression of MMP‐2 and ‐9 and play a key role in cancer invasion and metastasis." (PMID 35356799, 2022). "STAT3, one of the numerous transcription factors among those signal pathways, is closely related to the occurrence and development of cancer and is considered a promising target for cancer treatment." (PMID 36559280, 2022). "STAT3 activation can induce cancer-promoting inflammation mediated by nuclear factor-kappa B (NF-κB) and IL-6/GP130/JAK pathways while suppressing NF-κB- and STAT1-mediated Th1 antitumor immune responses by decreasing the expression of antitumor cytokines such as IL-12 and IFN." (PMID 36557902, 2022). "In particular, STAT3 has been identified as a regulator of inflammation and cancer." (PMID 35565420, 2022). "All compounds showed better activity against STAT3, P13 Kalpha and Human A. c-Kit Tyrosine Kinase and Protein Kinase B (Akt) were predicted to have a strong interaction potential against the cancer therapeutic targets with the best binding poses and a low binding energy." (PMID 36432091, 2022). "Generally, the CKS1B/STAT3 axis contributes to the development of cancer." (PMID 36405738, 2022). "The transcription factor STAT-3 is overexpressed and plays oncogenic roles in many cancers." (PMID 35683032, 2022). "As an oncogene, STAT3 plays a vital role in the development of several forms of cancer." (PMID 35463085, 2022). "Interleukin (IL)-6 family cytokines, such as IL-6 and IL-11, are defined by the shared use of the gp130 receptor for the downstream activation of STAT3 signaling and the activation of genes which contribute to the “hallmarks of cancer”, including proliferation, survival, invasion and metastasis." (PMID 35053592, 2022). "Furthermore, up-regulated expression of Ror1 can be mediated by STAT3 in various types of cancer cells, thereby promoting proliferation of cancer cells in Wnt5a-dependent or -independent manners." (PMID 35493090, 2022). "Hepatocyte growth factor (HGF) is mainly secreted by CAFs and binds to the receptor, MET, on cancer cells, which activates the downstream signaling involving AKT, ERK/MAPK, and STAT3, and then enhances cancer cell survival, EMT, migration, invasion, proliferation, and chemotherapy resistance." (PMID 35327514, 2022). "Stat3 is activated in cancer and stromal cells by inflammatory stimuli." (PMID 35170261, 2022). "Thus, the positive feedback and collaboration between STAT3 and NF-κB play critical roles in controlling communication between inflammatory and cancer cells." (PMID 35470375, 2022). "However, STAT3 can be differentially activated to regulate cancer cell phenotype and control their fate." (PMID 36499683, 2022). "Resveratrol might counteract the Interlukin-6 induction of cell migration in cancer cells via autophagy induction in the cells at the migration front, which was paralleled by downregulation of STAT3 expression and upregulation of ARH-I." (PMID 35566016, 2022). "Interestingly, multiple natural compounds have been identified to suppress STAT3 activity and exhibit anti-cancer properties." (PMID 35371975, 2022). "STAT3 seems to play a central role in inflammation-mediated cancer." (PMID 35267632, 2022). "In addition, high levels of phosphorylated STAT3 expression often result in a poor prognosis in many types of cancer." (PMID 36061181, 2022).
cancer (continued). "Moreover, while STAT3 phosphorylation was increased in both RM1- and mPEC-efferocytic BM macrophages, p-STAT3 levels were significantly higher in BM macrophage efferocytosis of apoptotic RM1 cancer cells vs. mPECs." (PMID 36496973, 2022). "Thus, STAT3 has been suggested as a more promising target for cancer therapy by redirecting inflammation." (PMID 36499154, 2022). "In addition, with CuB, arrest of the G2-M phase and induction of apoptosis in cancer cells was associated with the inhibition of JAK2, STAT3, and STAT5 by decreasing Bcl-xL." (PMID 36355498, 2022). "In this review, we summarize the latest advances in STAT3 pathway in cancer." (PMID 35356799, 2022). "The inhibition of STAT3 activation affects cancer cell proliferation and viability." (PMID 35956786, 2022). "However, the abnormal activation of this signaling pathway promotes the development of cancer: misregulation of STAT3 in cancer cells promotes pro-oncogenic inflammation and suppresses anti-tumor immunity." (PMID 36542668, 2022). "IL-12, vitamin D3, vitamin A, curcumin, and cucurbitacin B [a selective inhibitor of Janus kinase 2 (JAK2)/STAT3] are molecules that may induce MDSCs to differentiate into mature myeloid cells in several types of cancer." (PMID 36081407, 2022). "Nevertheless, STAT3 is a major drug target that induces the transcription of genes involved in the proliferation, migration, invasion, angiogenesis, drug resistance, and immunosuppression of cancer." (PMID 36551576, 2022). "This could be significant to explain the steering of L‐CTCL cancer cell metabolism and proliferation via cytokine‐triggered STAT3/5‐MYC axis." (PMID 36341492, 2022). "In view of its anti-apoptotic activity and activation frequency in cancers, STAT3 could be used as an appealing therapeutic target in a number of cancers." (PMID 35401182, 2022). "However, most of them also inhibited other signaling pathways in cancer cells and indicated a low level of specificity in targeting the STAT3 signaling pathway." (PMID 36231093, 2022). "Indeed, several studies have indicated that the STAT3 pathway mediates M1/M2 macrophage polarization during the development of cancer and other diseases." (PMID 36323670, 2022). "BCL3 activated STAT3, an aggressive oncogene in human cancer and promoted metastasis." (PMID 35399006, 2022). "The JAK/STAT3 signaling pathway plays a vital role in various types of cancer." (PMID 35517411, 2022). "Curcumin has an impact on cancer cell proliferation via regulating AP-1 and STAT3." (PMID 35530318, 2022). "The IL-6/STAT3 pathway is a classic signaling that can induce enhanced EMT process in cancers." (PMID 36304989, 2022). "Due to the role of STAT-3 in cancer initiation and development, multiple treatments aim to inhibit the IL-6/IL-6R/STAT-3 signaling pathway, one of these treatments is tocilizumab (Tcz), a humanized monoclonal antibody that binds to membrane-bound and soluble IL-6R to inhibit IL-6 signaling." (PMID 35703345, 2022). "Cachexia-relevant myocellular responses to STAT3 activation include the upregulation of SOCS3 that promotes insulin resistance, proteolysis and mitochondria dysfunction, all of which are implicated in cancer cachexia and its gender-related variability." (PMID 35626644, 2022). "Furthermore, STAT3 not only participates in the polarization of macrophages to M2 but also participates in the depletion of T cells, suggesting that STAT3 inhibition can be used as a new therapeutic strategy for the treatment of cancer." (PMID 36313455, 2022). "STAT3 is demonstrated to be a viable biomarker for invasiveness of cancer and metastasis, and it may provide a prediction of the need for more aggressive treatment." (PMID 36230984, 2022). "It has been described for its effects on the induction of apoptosis and cell cycle suppression through regulation of the EGFR/MAPK pathway or by inhibition of STAT3 and apoptotic activity in cancer cell lines of the cervix or lung and anti-inflammatory activity." (PMID 36355498, 2022).
cancer (continued). "IL-6 activation of STAT3 was found to downregulate miR-34a in cancer cells." (PMID 35740998, 2022). "In addition, all-trans retinoic acid (ATRA) showed great potential in cancer treatment through inhibition of p-STAT3 and p-JAK2." (PMID 36231093, 2022). "Therefore, STAT3 activation and glycan alterations are the promising therapeutic targets to overcoming multidrug resistance in cancer." (PMID 35281907, 2022). "Changes to the phosphorylation of Erk, Akt, and STAT3 could alter cancer cells’ sensitivity to gemcitabine treatment." (PMID 35804923, 2022). "Moreover, six cancer hallmark pathways contained interferon gamma response, protein secretion, interferon alpha response, MTORC1 signaling, JAK STAT3 signaling, and inflammatory response actively associated with the low-risk group." (PMID 35422861, 2022). "Therefore, the JAK/STAT signaling pathway, especially STAT3 signaling, has emerged as a promising drug target for cancer treatment strategies." (PMID 35216314, 2022). "For instance, N-4-hydroxyphenylretinamide (4-HPR) was highly bound at STAT3’s dimerization site and c-Abl and c-Src ATP-binding kinase sites to suppress cancer-promoting pathways including STAT3 phosphorylation, STAT3-DNA binding, and production of the trans-signaling enabling sIL-6R." (PMID 36231093, 2022). "A powerful example of SBT-100′s inhibitory and anti-inflammatory ability is also demonstrated by its ability to block the effect of IL-6 on cancer cells and normal cells in vitro by preventing STAT3 from transcribing target genes in the nucleus such as VEGF and PD-L1." (PMID 35886918, 2022). "Stat3-mediated upregulation of S100A8/9 promotes accumulation of MDSCs in cancer." (PMID 34976216, 2022). "STAT3 inhibitors, piperine, pyrimethamine, and salidroside, inhibit cancer cell metastasis." (PMID 35810312, 2022). "Our study concluded that MACC1 might be a novel regulator of CC by regulating the AKT/STAT3 pathway to change the migration, invasion, apoptosis, and cancer stemness of CC cells." (PMID 34939526, 2022). "While NF-κB and TGFβR1/Smad signaling played a role in platelet-induced PD-L1 expression, we could not find any significant change in phosphorylation of STAT-1 or STAT-3 in platelet-exposed cancer cells." (PMID 35626102, 2022). "Signal transducer and activator of transcription 3 (STAT3) is an important transcription factor that not only regulates different hallmarks of cancer, such as tumorigenesis, cell proliferation, and metastasis but also regulates the occurrence and maintenance of cancer stem cells (CSCs)." (PMID 36559280, 2022). "LC3B, the most potential molecular biomarker of autophagy that may promote or inhibit cancer progression, can be downregulated by STAT3." (PMID 35057825, 2022). "IL-10 secretion directed by STAT3 in cancer cells also results in the arrest of antitumor immunity." (PMID 35401182, 2022). "Notably, accumulation of inflammatory mediators, such as transcription factors NFκB and STAT3 as well as cytokines IL-6 and TNF-α, has been linked to local and systemic immunosuppression associated with the progression of cancer." (PMID 35163219, 2022). "Signal transducer and activator of transcription 3 (STAT3) is becoming part of the most prevalent studies in anti-cancer therapy, owing to its inhibition reported to trigger a variety of cell apoptosis in hematologica and solid cancers that show constitutive STAT3 activation." (PMID 35651786, 2022). "Interestingly, lactate itself induces the expression of GPR81 in cancer cells by transcriptional activation involving the Snail/EZH2/STAT3 transcription complex." (PMID 36230479, 2022). "Some of the significant cancer hallmark terms are epithelial-mesenchymal transition (MSX1, CXCL12, SCG2, SLIT2), KRAS signaling up (F13A1, ADAMDEC1), inflammatory response (CCL5, VIP), IL-6/JAK/STAT3 signaling (CXCL13)." (PMID 35486660, 2022).